TAP1 (transporter 1, ATP binding cassette subfamily B member)
Diseases named in the same sentence as TAP1 in open-access papers (continued):
Sharing a sentence is not in itself a finding about the gene and the disease.
tumor (continued). "TMB and MSI are reported biomarkers that can predict TME status and anti-tumor efficacy of ICI therapy, and used Spearman’s correlation analysis to test the correlations of TMB and MSI with TAP1 expression." (PMID 36759763, 2023). "Knockout of TRIM21 resulted in high expression of HLA-A, B2M, TAP1 and TAP2 in SUNE1 tumour cells isolated from BALB/c nude mice and of B2m, Tap1, Tap2, Tapbp and Earp1 in MC38 tumour cells isolated from C57BL/6 mice." (PMID 36797289, 2023). "To determine the effect of TAP1 on the proliferative activity and metastatic migration ability of tumor cells in UVM, we successfully knocked down TAP1 expression in C918 cells using TAP1 siRNA." (PMID 36774490, 2023). "Furthermore, a knock-down of TAP-1 gene or epigenetic changes and TAP-1 protein downregulation, as well as the loss of tapasin, an essential component of the peptide-loading complex (PLC) in human cancer cells, elicits tumour immune escape by inhibiting CTL surveillance against the tumour." (PMID 36980527, 2023). "According to previous findings, low expression of ATM, TAP1 and LCN2 will increase the sensitivity of tumor cells to cisplatin, which is the same as our study conclusion and further illustrates the accuracy of our method." (PMID 36016575, 2022). "Most MHC I molecules, including HLA-A, HLA-C, HLA-E, HLA-F, TAP1, TAP2, and TAPBP (all P < 0.05), were upregulated in PTPRD/PTPRT mutant patients, indicating enhanced anti-tumor immunity in PTPRD/PTPRT mutant patients." (PMID 36248841, 2022). "TAP1 displays high expression in side population (SP) cells in PDAC, and SP cells have higher chemoresistance in comparison to other tumor cells, which was considered the candidate to the cancer stem cells." (PMID 36419887, 2022). "At the protein level, the upregulation of p-STAT3, TAP1, β2M (MHC-I-related protein) and PD-L1 were also observed in MC38 tumor tissues." (PMID 34976211, 2022). "Specifically, CCND1 amplified tumor tissues exhibited decreased mRNA expression of CD8, Gzm, B2m and Tap1 and significantly lower proportions of CD8 T cell and T follicular helper cells." (PMID 35844619, 2022). "Since TAP1 and HLA-DQA1 function in antigen presentation processes that allow T cells to recognize and kill tumor cells, we examined the prognostic value of their combined IHC values." (PMID 35173148, 2022). "In theory, the downregulation of the expression of TAP1 can lead to the decreased MHC-I complexes on the cell membrane, so that tumor cells can escape cytotoxic T cell recognition." (PMID 36419887, 2022). "This means that, in combination with the previously reported expression of other antigen processing proteins such as TAP1 and TAP2, the essential components of the antigen presentation pathway are present in the tumor cells of HL." (PMID 33499248, 2021). "Our results indicated that lipotecan upregulates TAP1 and MHC class I expression to facilitate tumor antigen presentation, thereby attracting cytotoxic T lymphocyte infiltration." (PMID 33799527, 2021). "In order to determine the expression levels of HLA-I/APM components in OSCC, protein expression of HLA-I HC, β2-m and the APM molecules TAP1, TAP2, LMP2 and LMP10 were analyzed by IHC of formalin-fixed, paraffin-embedded (FFPE) tumor lesions." (PMID 33557271, 2021). "PSMB8, PSMB9, PSMB10, PSME2, TAP1, and IRF1 promote CD8+ T cell infiltration by enhancing MHC class I tumor antigen processing." (PMID 33330025, 2020). "Eight co-expressed genes (PSMB8, PSMB9, PSMB10, PSME2, TAP1, IRF1, FBOX6, ETV7) were identified as CD8+ T cell-related genes that promoted infiltration of CD8+ T cells, and were enriched in the MHC class I tumor antigen presentation process." (PMID 33330025, 2020).
tumor (continued). "The process of hiding the tumor identity involves major histocompatibility complex (MHC) I-related genes (e.g., HLA-A/B/C, TAP1/2, TAPBP, and B2M)." (PMID 31737562, 2019). "Our analysis also revealed modest expression of the HLA genes, including low expression of peptide transporters TAP1 and TAP2, in the LS-CRC tumour." (PMID 30108227, 2018). "Importantly, Ptgs1/Ptgs2−/− tumors were able to grow in Rag1−/−, Tap1−/−, and Batf3−/− hosts, indicating that prostanoid deficiency did not impair tumor formation in a cell-intrinsic fashion but rather acted to prevent CD8α+/CD103+ DC-dependent rejection mediated by CD8+ T lymphocytes." (PMID 26343581, 2015). "While mice immunized with either high or low dose of B7.1-expressing TAP1+ cells rejected TAP− tumors, only high dose immunization with B7.1-expressing TAP− cells resulted in tumor rejection." (PMID 19629186, 2009). "However, in many cases, human cancer exhibits a TAP-negative phenotype, and thus it is still unclear whether B7.1 expression in these tumor cells can elicit the protective T-cell immunity or whether expression of both B7.1 and TAP1 genes is required to generate such immunity." (PMID 19629186, 2009). "Three important factors, TAP1, B7.1 and the amount of antigen(s) appear to contribute to CMT.64 tumor cell priming of T cells." (PMID 19629186, 2009). "To evaluate the effects of B7.1 expression on TAP1-positive and TAP-negative tumor cells on antitumor immunity, we first analyzed expression of the introduced genes in CMT.64 transfectants." (PMID 19629186, 2009). "A number of other immune genes, including MHC class I, components of the class I peptide presentation pathway (TAP1, TAP2, LMP2, LMP7 and Tapasin), B7-1/2, NKG2D ligands and certain tumor antigens, are also silenced by chromatin in multiple tumor types." (PMID 18070359, 2007). "Analysis of tumors from ApcMin/+/Ptpn13fl/fl/Vil-CreERT2 (APV) mice showed that Ptpn13 knockout, induced by TAM treatment, significantly upregulated the expression of IRF1, LMP2, TAP1, TAP2, H2-D1, H2-K1, and B2M and also increased the surface levels of MHC-I complex on tumor cells." (PMID 41486293, 2026). "While GBM tumours frequently exploit immune evasion mechanisms such as PD-L1 overexpression, MHC-I downregulation, and impaired antigen presentation via TAP1/TAP2 suppression, translation of these findings into effective immune checkpoint inhibitor (ICI) therapies has proven challenging." (PMID 41179304, 2025). "Defects in the TAP1 gene, a component of the antigen processing machinery, and the HLA Class I genes (HLA-A, HLA-B, and HLA-C) enable tumor cells to evade immune destruction by CD8+ T cells due to impaired presentation of tumor antigens." (PMID 41295262, 2025). "We also acknowledge limitations in the determination of cancer cell TAP1/2 protein downregulation using QIF due to the lack of a well established biological references to determine relevant cut-points in human tumor specimens." (PMID 40091029, 2025). "Using multiplexed immunofluorescence, we spatially mapped CD8+ effector Tumor-Infiltrating Lymphocytes (TILs) and the APM components TAP1 and TAP2 in 819 baseline/pre-treatment NSCLCs from patients treated with and without PD-1 axis blockers in 4 independent cohorts." (PMID 40091029, 2025). "However, a subset of cases showed marked reduction of TAP1 and/or TAP2 only in cancer cells (CK+) with preservation of the signal in the neighboring non-tumor lung tissue and/or stromal cells (CK-) supporting cancer cell selective protein downregulation." (PMID 40091029, 2025). "Moreover, TLC388 also upregulated antigen processing proteins such as TAP1 and MHC class I expression, enhancing tumor antigen presentation and attracting infiltration of cytotoxic T lymphocyte." (PMID 38564022, 2024). "Immunofluorescence images of cell lines derived from tumor and non-tumor tissue were analyzed to determine TAP1 protein distribution at the subcellular level." (PMID 36759763, 2023).
tumor (continued). "We next tested the association of primary/metastasis-specific downregulation of an MHC class I metagene signature composed of a composite expression of HLA-A, HLA-B, HLA-C, B2M, TAP1, TAP2 and NLRC5 between metastasis and matched primary tumor according to intrinsic subtype." (PMID 36585450, 2023). "TAP1 and MHC-I play crucial roles in tumor antigen recognition by Cytotoxic CD8+ T cells." (PMID 38106208, 2023). "Bioinformatic study with large datasets demonstrated a correlation between the TAP1 gene and tumor progression and a significant negative correlation for TAP1 gene expression and the survival rate in different cancer types." (PMID 35123499, 2022). "KRAS-Mut tumors showed significant upregulation of tumor migration (TGFBR2-S553 and EPHB3) and PI3K/AKT activation (PIP4K2C and PIK3R1), while the KRAS-WT group was enriched in immune regulation (TAP1/2, IFITM1, and IFIH1-S301) and cellular metabolism (DGAT1 and HINT3)." (PMID 35836817, 2022). "This study suggests that TAP1 may affect these pathways in PDAC and then remodel the tumor environment to promote tumor growth." (PMID 35806187, 2022). "The expression levels of B2M(p = 2.926e-05), HLA-C(p = 2.628e-03), HLA-E(p = 5.5166e-08), HLA-F(p = 9.376e-03), TAP1(p = 1.972e-09), TAP2(p = 1.245e-04) and TAPBP (p = 2.652e-12)in tumor tissues of dMMR patients were significantly higher than those of pMMR patients." (PMID 36527024, 2022). "As demonstrated in studies with a pharmacological inhibitor and TAP1 knockout MDA-MB-231 cells treated with inCT†CMVp480–516, a TEDbody delivers MHC-I-restricted peptides into the cytosol of target tumor cells for pMHCI presentation through the endogenous MHC-I antigen presentation pathway." (PMID 35459256, 2022). "The importance of antigen presentation in immune-oasis SCLC is further supported by MHCII-related molecules, such as HLA-B, TAP1, and CD74, which are all extensively overexpressed in this tumor phenotype and strongly interconnected according to string maps and network analysis." (PMID 34200100, 2021). "A previous study reported the functional significance of TAP1 (but not TAP2) expression in tumour cells." (PMID 33128234, 2020). "Moreover, the expression levels of Interferon regulatory factor (Irf)-1, and its downstream targets Tap1 and H2-Kb (one of the MHC-I genes) were consequently also strongly inhibited in both tumor cell lines in OGD conditions." (PMID 31196219, 2019). "In these experiments, we verified that DCI, epoxomicin, EER and siRNA targeting SPP and TAP1 had no or only a weak effect on tumour cell viability and cell surface expression of HLA-A2 molecules." (PMID 30504837, 2018). "MEL 22 showed a mixed B and C pattern, with tumor cells homogeneously stained for HLA class I but undetectable transporter for antigen presentation TAP-1 (data not shown)." (PMID 27484791, 2016). "This latter phenotype, tumor cells positive for class I and negative for TAP-1, was observed also in sample MEL26, collected from a progressing NB patient." (PMID 27484791, 2016). "In particular, B7.1 transfected TAP1-expressing RMA-S cells can elicit T-cell clones reacting with TAP1 or TAP2 deficient tumor cells, but not with TAP-competent tumor cells." (PMID 19629186, 2009). "We also observed that tumor cells that engaged senescence-related transcriptional programs, or “Sen-High” cells, upregulated IFN-γ signaling machinery, including Ifngr1, Ifngr2, Jak1, Jak2, Irf1, and Stat1, as well as IFN-γ target genes Cxcl9, Cxcl10, and Tap1." (PMID 40299790, 2025). "Previous experiments indicating that TAP1 is downregulated in cancer cells were conducted at the cellular level, while our results were derived from a tissue-based analysis, with no separation of tumor cells from adjacent mesenchyme." (PMID 36759763, 2023). "Similarly, PD-L1 and β2M were upregulated in tumor cells under nintedanib (1 μM) treatment, while TAP1 had no obvious effect." (PMID 34976211, 2022).
tumor (continued). "Given TAP1 expression increased tumor growth in vivo and overexpression of ABC transporters are predominantly found in cancer stem cells (CSCs), we supposed that TAP1 expression could promote tumor stemness." (PMID 35806187, 2022). "IHC staining of tumor samples showed that the expression of TAP1 was not influenced by trametinib." (PMID 35806187, 2022). "Additionally, upregulated antigen-presenting machinery comprising TAP1, TAP2, and MICB suggested that the cytotoxic T cells could be selectively programmed against tumor cells." (PMID 35884843, 2022). "Moreover, lipotecan remarkably with radiotherapy enhances TAP1 and MHC class I expression for antigen presentation, reinvigorating cancer immunogenicity for tumor-specific T cell activation and leading to favorable complete regression ability in vitro and in vivo." (PMID 33799527, 2021). "Thus, no relevant comparison between TAP1 in tumor-free samples of SCCOT and the clinical outcome was possible using TCGA patient samples." (PMID 32867395, 2020). "In addition a set of 15 proteins that participate in the antitumor immune response such as the tumor suppressors PSMB9, ERAP1 and TAP1 or the interferon-stimulated genes IFIT1 and MX1 were found down-regulated in CUL4A-overexpresing cells and up-regulated in CUL4A-silencing models." (PMID 24870930, 2014). "In each tumor cell line, exposure to radiation significantly increased the expression of ≥ 6 APM components by ≥ 30%, namely the immunoproteosome subunits LMP2, LMP7, and LMP10; the peptide transporters TAP1 and TAP2; and the chaperones calnexin (2/3 cell lines) and tapasin (3/3 cell lines)." (PMID 24480782, 2014). "Indeed, the defective TAP1 and LMP2 expression in these tumors is associated with a G871E mutation in the ATP-binding region of the JAK1 kinase domain, thereby affecting JAK1 kinase activity, but neither JAK1 expression nor its degradation allow the tumor cells to evade anti-tumor specific immunity." (PMID 37047709, 2023). "Genes of the antigen-processing machinery and regulation (IRF1, IRF2, NF-κB1, NF-κB2, NLRC5, TAP1, TAP2, TAPBP) were not significantly expressed throughout all of the analyzed tumor transcriptomes." (PMID 35892842, 2022). "The poor immunogenicity of the B16F10 mouse tumor model has been attributed to a lack of effective antigen presentation due to epigenetic suppression of APM, including MHC Class I, MHC Class II and Tap-1." (PMID 30323352, 2019). "In contrast, ENHO exhibited negative co-expression with MHC class I-related genes (TAP1, TAP2, and TAPBP), which may reflect a tumor-driven mechanism aimed at evading cytotoxic T cell-mediated immune surveillance." (PMID 40647442, 2025).
cancer (87 papers, 2009 to 2025). A tumor composed of atypical neoplastic, often pleomorphic cells that invade other tissues. "A similar reduction in the levels of surface HLA-I proteins (HLA-ABC) was seen in TAP1/2 deficient cancer cells, supporting reduced membrane stabilization of HLA-peptide complexes." (PMID 40091029, 2025). "The TAP1 gene has seven alleles, and TAP1 polymorphisms are linked to various types of cancer carcinogenesis, such as protective risk or precipitating risk." (PMID 38357083, 2024). "Defects in antigen presentation machinery have been well-described across a spectrum of human cancer types – including mutations in TAP1 and PSMB8 like the ones we observed in CT2A-luc." (PMID 38213329, 2023). "Based on the results of single cell and prognostic analyses, we concluded that TAP1 expression in lymphocytes has a role in cancers and that those with high TAP1 expression are associated with better patient prognosis." (PMID 36759763, 2023). "Forest plots of univariate Cox regression analysis of OS data indicated that the association of TAP1 with survival probability varied among the 32 cancer types, with TAP1 a risk factor for 11 cancer types and a protective factor for 8 types." (PMID 36759763, 2023). "Given the significant prognostic value of TAP1 in various cancers, we further investigated the underlying biological processes or pathways associated with TAP1, to understand the potential mechanisms involved." (PMID 36759763, 2023). "TAP1 expression was detected as associated with both increased risk and protection, suggesting a distinct effect of TAP1 in each cancer." (PMID 36759763, 2023). "The gene mutation analysis at the pan-cancer level suggested the relatively lower mutation of TAP1 at the genome level of patients with KIRC." (PMID 36419887, 2022). "Considering that the expression of TAP1 is associated with drug resistance in increasing types of cancers, we chose the CellMiner database to analyze the relationship between TAP1 expression and drugs." (PMID 36419887, 2022). "Transporter associated with antigen processing 1 (TAP1) is a protein related immune regulation and plays a role in several malignant tumors." (PMID 34957213, 2021). "Histone acetylation of the TAP1 promoter was proposed as a potential repressor mechanism accounting for TAP1 deficiency in various carcinoma cell lines." (PMID 25699047, 2015). "However, the correlation between TAP1 and RNA modification-associated enzyme was observed in most of cancers, indicating an engagement of RNA methylation in post-translation regulation." (PMID 36419887, 2022). "Thus, the study has designed to analyze the association between the TAP1 with cancer by computationally." (PMID 34047812, 2021). "The association of TAP1 in cancer progression remains mostly unknown and further study of the gene in relation with cancer need to conduct." (PMID 34047812, 2021). "The TAP1/2 and β2m proteins are frequently mutated in different cancer types." (PMID 33784856, 2021). "The TAP1 encoded protein is involved in the processing of antigens it contributes to anti-cancer drug resistance and hence, has an effect on the survival rates of patients and can play a part in cancer progression due to its MDR activity." (PMID 34047812, 2021). "Only TAP1 D637G polymorphism was found to be associated with cancer risk, which was significantly increased for carriers of at least one G allele (OR, 1.659; 95 % CI, 1.112–2.474) and heterozygote carriers of the variant allele G (OR, 1.626; 95 % CI, 1.080–2.449)." (PMID 26205887, 2015). "However, the essential function of TAP1 and its underlying mechanism in regulating the chemosensitivity of human cancer remain largely unknown." (PMID 35806187, 2022). "Finally, alterations in antigen processing, such as downregulation of Transporter Associated with Antigen Processing 1 (TAP1) expression, have been reported in a variety of different cancer types and have been shown to limit antigen recognition by the immune system." (PMID 26883197, 2016).